ADRA1B (adrenoceptor alpha 1B)
Description:
Alpha-1 adrenergic receptors are G protein-coupled receptors for catecholamines that signal through the G(q) family of G proteins, including G(q) and G(11). Upon activation, they stimulate the phosphatidylinositol-calcium second messenger pathway, leading to calcium release from intracellular stores and activation of protein kinase C (By similarity). ADRA1B binds the catecholamine ligands norepinephrine and epinephrine. Can also couple to G(14) and G(16) proteins (By similarity). Nuclear ADRA1B forms heterooligomers with ADRA1A to regulate phenylephrine(PE)- stimulated ERK signaling in cardiac myocytes. At the plasma membrane, ADRA1B interacts with CAVIN4/MURC to regulates ERK activation in cardiomyocytes, contributing to the regulation of cardiac hypertrophy.
Synonyms: ADRA1; ALPHA1BAR
Tractability: Small molecule: an approved drug acts on it; a high-quality ligand is known; it belongs to a druggable protein family. Antibody: UniProt places it where antibodies can reach, with high confidence; its Gene Ontology location is reachable by antibodies, with high confidence; UniProt predicts a signal peptide or a membrane-spanning region; the Human Protein Atlas places it where antibodies can reach. PROTAC: a small molecule that binds it is known. Other modalities: an approved drug acts on it.
Target class: Small molecule receptor (family A GPCR); Adrenergic receptor; Monoamine receptor; Membrane receptor; Family A G protein-coupled receptor
Chemical probes: TERAZOSIN
Safety:
Unwanted effects reported when the protein is acted on. In parentheses: how it was acted on, where the effect was seen, and who reports it.
cardiac hypertrophy (activation, acute dosing; nervous system, renal, cardiovascular; source: Lynch et al. (2017))
convulsions (activation, acute dosing; nervous system, renal, cardiovascular; source: Lynch et al. (2017))
decreased blood pressure (inhibition, acute dosing and activation, acute dosing; nervous system, renal, cardiovascular; source: Lynch et al. (2017))
decreased locomotor activity (activation, acute dosing; nervous system, renal, cardiovascular; source: Lynch et al. (2017))
neurodegeneration (activation, acute dosing; nervous system, renal, cardiovascular; source: Lynch et al. (2017))
orthostatic hypotension (activation, acute dosing; nervous system, renal, cardiovascular; source: Lynch et al. (2017))
Gene: Protein-coding gene on chromosome 5 (159,865,080 to 159,973,012, forward strand). Ensembl gene ENSG00000170214.
Subcellular location: Nucleus membrane; Cell membrane; Cytoplasm; Membrane, caveola
Subcellular location (Human Protein Atlas): Plasma membrane
Pathways (Reactome):
Signal Transduction: Adrenoceptors; G alpha (12/13) signalling events; G alpha (q) signalling events
Gene Ontology:
Molecular function: protein binding; protein heterodimerization activity; alpha1-adrenergic receptor activity; adrenergic receptor activity; G protein-coupled receptor activity
Biological process: phospholipase C-activating G protein-coupled receptor signaling pathway; positive regulation of cardiac muscle hypertrophy; positive regulation of MAPK cascade; adenylate cyclase-activating adrenergic receptor signaling pathway; adenylate cyclase-modulating G protein-coupled receptor signaling pathway; cell-cell signaling; G protein-coupled receptor signaling pathway; intracellular signal transduction; neuron-glial cell signaling; positive regulation of cytosolic calcium ion concentration; regulation of cardiac muscle contraction; regulation of muscle contraction; regulation of vasoconstriction
Cellular component: cytoplasm; nuclear membrane; nucleus; plasma membrane; caveola; membrane
Genetic constraint (gnomAD): Loss-of-function variants: 17 observed, 17.58 expected, observed/expected ratio (o/e) 0.97, 90% interval 0.66 to 1.45. The synonymous counts are far from expectation, so gnomAD's model fits this gene poorly and the ratio says little. Missense variants: 680 observed, 614.32 expected, observed/expected ratio (o/e) 1.11, 90% interval 1.04 to 1.18. Synonymous variants: 366 observed, 277.32 expected, observed/expected ratio (o/e) 1.32, 90% interval 1.21 to 1.44.
Homologues: Orthologues: chimpanzee ADRA1B (99% identical), macaque ADRA1B (99% identical), pig ADRA1B (98% identical), mouse Adra1b (95% identical), rat Adra1b (95% identical), dog ADRA1B (94% identical), guinea pig ADRA1B (94% identical), rabbit ADRA1B (92% identical), zebrafish adra1bb (54% identical), zebrafish adra1ba (54% identical), tropical clawed frog adra1b (52% identical), Caenorhabditis elegans ser-5 (24% identical). Paralogues in human: ADRA1D (48% identical), ADRA1A (44% identical), ADRB1 (26% identical), ADRB3 (26% identical), DRD2 (25% identical), ADRA2B (24% identical), ADRA2C (24% identical), ADRB2 (23% identical), ADRA2A (23% identical), GPR101 (18% identical), OR5T1 (12% identical), OR13F1 (12% identical), and 6 more.
Diseases named in the same sentence as ADRA1B in open-access papers:
ADRA1B is named in the same sentence as 36 diseases in open-access papers, as found by Europe PMC text mining. Sharing a sentence is not in itself a finding about the gene and the disease. The quoted sentences say what the papers report.
Arrhythmia (2 papers, 2021 to 2022). Any cardiac rhythm other than the normal sinus rhythm. "The PPI k-means classification results suggested that 25 genes, iADORA1, ADORA2B, ADRA1A, ADRA1B, and ADRA1D, play a more important role in arrhythmia pathology and PRP treatment." (PMID 34393777, 2021).
asthma (2 papers, 2022 to 2024). "According to RNA-Seq results for HASM cells derived from age- and sex-matched fatal asthma or nonasthma lung donors, both the ADRA1A and ADRA1B genes (encoding α1AR subtypes A and B) were expressed." (PMID 35787178, 2022). "Of note, levels for ADRA1B and ADRB2 varied according to donor, but were not significantly different by asthma status." (PMID 35787178, 2022).
colorectal cancer (2 papers, 2007 to 2025). A primary or metastatic malignant neoplasm that affects the colon or rectum. "In all four of these colorectal cancers, methylation was limited to Region 3 and Region 4 in ADRA1B promoter." (PMID 17242706, 2007). "In this study, we used the MS-RDA technique to analyse two human colorectal cancers and newly identified alpha-1B-adrenergic receptor (ADRA1B)." (PMID 17242706, 2007). "ADRA1B promoter methylation was detected by MSP in four of 34 (11.8%) colorectal cancers." (PMID 17242706, 2007). "Thus, ADRA1B promoter methylation was a cancer-specific event in the colorectal cancers and surrounding epithelial tissues." (PMID 17242706, 2007). "In colorectal cancers, only a subset of tumours showed aberrant ADRA1B promoter methylation." (PMID 17242706, 2007). "In colorectal cancers, only four of 34 (11.8%) tumours showed ADRA1B promoter methylation." (PMID 17242706, 2007). "The results showed that, compared with normal tissues, the expression of ADRA1B, CDKN2A, FCER2, and IL13 was significantly upregulated in colorectal cancer tissues, while CALM1, CTNNA1, GSR, INSR, and MAPK9 were significantly downregulated." (PMID 40696679, 2025).
gastric cancer (2 papers, 2007 to 2021). A primary or metastatic malignant neoplasm involving the stomach. "ADRA1B is an alpha-adrenergic receptor whose action is mediated by association with G proteins; in gastric cancer it was found a methylation promoter and it could be frequently involved in development and gastric cancer progression." (PMID 33649335, 2021). "Our results suggest that the ADRA1B gene is an important tumour-related gene frequently involved in the development and progression of gastric cancer." (PMID 17242706, 2007). "In conclusion, our study showed that ADRA1B promoter is aberrantly hypermethylated in colorectal and gastric cancers." (PMID 17242706, 2007). "Reverse transcription–PCR detected reduced ADRA1B expression in 12 of 18 (66.7%) gastric cancers, and its promoter methylation was detected in 11 of these 12 (91.7%) gastric cancers with reduced ADRA1B expression." (PMID 17242706, 2007). "We also demonstrated that ADRA1B promoter methylation occurred in the surrounding epithelial tissues of gastric cancers, a small fraction of which concurrently had reduced ADRA1B expression." (PMID 17242706, 2007). "In gastric cancer, ADRA1B promoter methylation occurs frequently in both cancer tissue as well as in surrounding epithelial tissue." (PMID 17242706, 2007). "In contrast, ADRA1B promoter methylation was detected in 24 of 34 (70.6%) gastric cancers and in 14 of 34 (41.2%) surrounding epithelial tissues." (PMID 17242706, 2007). "ADRA1B promoter methylation was detected in 24 of 34 (70.6%) gastric cancers and in 14 of 34 (41.2%) surrounding epithelial tissues." (PMID 17242706, 2007). "In contrast, ADRA1B promoter methylation was found much more frequently not only in gastric cancers but also in their surrounding epithelial tissues, and the majority of gastric cancers with ADRA1B promoter methylation had reduced ADRA1B expression." (PMID 17242706, 2007). "Semiquantitative RT–PCR detected reduced ADRA1B expression in 12 of 18 (66.6%) gastric cancers and three of 18 (16.4%) surrounding tissues." (PMID 17242706, 2007). "In 10 analysed gastric cancers, the results of bisulphite sequencing of ADRA1B promoter methylation were concordant with those of MSP regarding the extent of the methylation area." (PMID 17242706, 2007). "Among the 34 gastric cancers, ADRA1B promoter methylation was detected in Region 1 in 12 cancers (35.3%), Region 2 in 14 (41.2%), Region 3 in 18 (52.9%), and Region 4 in 23 (67.6%)." (PMID 17242706, 2007). "Our results suggest that ADRA1B is an important tumour-related gene with key roles in the development and progression of gastric cancer." (PMID 17242706, 2007). "Therefore, 5q LOH is apparently related to reduced ADRA1B expression in a subset of gastric cancers." (PMID 17242706, 2007). "Furthermore, in gastric cancers, the ADRA1B promoter was very frequently methylated, generally in association with reduced ADRA1B expression." (PMID 17242706, 2007). "Our results first demonstrated ADRA1B promoter methylation in colorectal and gastric cancers." (PMID 17242706, 2007). "Three of 11 (27.3%) gastric cancers with reduced ADRA1B expression also had 5q LOH." (PMID 17242706, 2007). "Thus, ADRA1B promoter is frequently methylated in gastric cancer." (PMID 17242706, 2007).
myocardial infarction (2 papers, 2017 to 2022). Gross necrosis of the myocardium, as a result of interruption of the blood supply to the area, as in coronary thrombosis. "Our present study further revealed the remodeling of the Adra1b networking following myocardial infarction (group IN) and normalization by the post-myocardial infarction stem cell treatment (group IT)." (PMID 36013195, 2022).
papillary thyroid carcinoma (2 papers, 2022 to 2024). "ADRA1B is a member of the GPCRs, and it has been reported that this gene is closely related to the prognosis of thyroid papillary carcinoma." (PMID 35422890, 2022).
renal failure (2 papers, 2016). "The alpha1B-adrenoceptors (Adra1b) are involved in blood vessel remodeling and mediate the vasoconstrictor actions of the renal sympathetic nerves in rats with renal failure." (PMID 26821914, 2016).
Anxiety (1 paper, 2023). Intense feelings of nervousness, tension, or panic often arise in response to interpersonal stresses. "It has been reported that miR-483-5p and miR-699p-5p influence anxiety induced by physical or psychological stress via targeting corticotropin-releasing hormone receptor 1 (Crhr1) and Adrenoceptor Alpha 1B (Adra1b) mRNAs." (PMID 36979479, 2023).
breast tumors (1 paper, 2015). "For the ADRA1B gene, which encodes adrenoceptor alpha 1B, a previous study showed this gene is highly expressed in breast tumors with increased tumor recurrence and poor clinical outcome, suggesting this gene may perform a cancer-promoting role." (PMID 26870154, 2015).
cardiac failure (1 paper, 2019). "However, young Pgc-1β-/- showed reduced α1B-adrenergic receptor (Adra1b) transcription compared to young WT known to mediate protective and adaptive functions preventing pathological remodeling in cardiac failure through Gq/11 signaling." (PMID 31068841, 2019).
colon tumor (1 paper, 2020). "DUOXA2, CEACAM7, and the proto-oncogene ADRA1B were downregulated by calcitriol in rectal tumor organoids, but upregulated in colon tumor organoids." (PMID 32824266, 2020).
Glucose intolerance (1 paper, 2024). Glucose intolerance (GI) can be defined as dysglycemia that comprises both prediabetes and diabetes. "Here, we show that female, but not male, mice are more susceptible to obesity, glucose intolerance, and insulin resistance in the absence of liver Adra1b." (PMID 39259165, 2024). "However, loss of Adra1b in hepatocytes exacerbated diet-induced obesity, insulin resistance, and glucose intolerance in female, but not in male mice." (PMID 39259165, 2024).
Hypertension (1 paper, 2012). The presence of chronic increased pressure in the systemic arterial system. "Multiple SNPs within both PNMT (3 SNPs) and ADRA1B (7–8 SNPs) were associated with hypertension, DBP, and SBP." (PMID 22615923, 2012). "Multiple genes within the ADRA1 pathway were associated with hypertension and DBP, with the PNMT gene and the ADRA1B gene displaying the strongest associations." (PMID 22615923, 2012). "Of the three alpha 1 adrenergic receptor isoforms (ADRA1A, ADRA1B, ADRA1D), ADRA1B showed the strongest association with hypertension (Pgene<0.005), DBP (Pgene<0.02), and SBP (Pgene<0.02)." (PMID 22615923, 2012). "Within the ADRA1 pathway, the genes PNMT (hypertension Pgene<0.004, DBP Pgene<0.004, and SBP Pgene<0.009, and ADRA1B (hypertension Pgene<0.005, DBP Pgene<0.02, and SBP Pgene<0.02) displayed the strongest associations." (PMID 22615923, 2012). "However, the ADRA1B receptor has been linked to systolic blood pressure in a study of 427 young Caucasians, and ADRA1B antagonists (L-765,314, prazosin, terazosin) are commonly used to treat and investigate hypertension." (PMID 22615923, 2012). "Furthermore, when all SNPs within the ADRA1 receptor genes (ADRA1A, ADRA1B, ADRA1D) were removed from the model, the ADRA1 pathway remained associated with hypertension and DBP, suggesting that the observed pathway association was driven by genetic variants in several genes." (PMID 22615923, 2012). "SNPs in ADRA1B and PNMT have not previously been linked to hypertension in a genome-wide association study, but both genes have shown associations with hypertension through linkage or model organism studies." (PMID 22615923, 2012).
mild cognitive impairment (1 paper, 2022). "The results of the target-component network analysis showed that ADRB2, ADRA1B, DPP4, ACHE and ADRA1D played a key role in the treatment of mild cognitive impairment." (PMID 35646138, 2022).
Obesity (1 paper, 2024). Accumulation of substantial excess body fat. "Given these slight changes in glucose metabolism, we next sought to determine the metabolic role of liver ADRA1B in a context of diet-induced obesity (DIO)." (PMID 39259165, 2024). "Therefore, it is plausible that catecholamines increased as a compensation to the absence of liver Adra1b, which could have been even higher in combination with obesity." (PMID 39259165, 2024).
pterygium (1 paper, 2025). A wedge-shaped fibrovascular lesion arising from the bulbar conjunctiva and extending to the cornea. "The increased expression of TH, ADRA1A, ADRA1B, and ADRB2 suggests the involvement of the sympathetic system in the pathogenesis of pterygium." (PMID 40806545, 2025).
thyroid cancer (1 paper, 2022). "However, our study demonstrated that the GJB4 and ADRA1B genes may not be able to promote the thyroid cancer progression and development, and it may even be a protective gene." (PMID 35372518, 2022).
thyroid disease (1 paper, 2024). "We have identified ADRA1B as a significant gene associated with thyroid disease." (PMID 39697868, 2024).
cancer (9 papers, 2007 to 2024). A tumor composed of atypical neoplastic, often pleomorphic cells that invade other tissues. "It was reported that GJB4 and ADRA1B genes play an essential role in developing many malignant tumours." (PMID 35372518, 2022). "For each region, the frequency of ADRA1B promoter methylation was lower in the surrounding epithelial tissues than in the cancers; however, similar to the cancers, the frequency of ADRA1B promoter methylation was highest in Region 4 in the surrounding epithelial tissues." (PMID 17242706, 2007).
ADRA1B also shares sentences with these, for which no sentence is quoted: tumor (4 papers); insomnia (2); autonomic dysfunction (1); breast carcinoma (1); cardiac hypertrophy (1); dilated cardiomyopathy (1); infection (1); Insulin resistance (1); ischemia (1); learning disorders (1); lung carcinoma (1); pancreatic cancer (1); psoriasis (1); psychiatric disorder (1); pulmonary hypertension (1); rectal tumor (1); rheumatoid arthritis (1).